KIFC1 (kinesin family member C1)
Diseases named in the same sentence as KIFC1 in open-access papers (continued):
Sharing a sentence is not in itself a finding about the gene and the disease.
tumor (continued). "We then compared the nuclear KIFC1 WI values for normal and tumor samples and also across grades for tumor samples." (PMID 26992853, 2016). "Among the significant genes that show a high expression in tumours with unfavourable outcome, cell cycle associated genes can be found (E2F1, CCNA2, CCNB1, KIFC1)." (PMID 17531100, 2007). "Elevated KIFC1 levels are important for tumorigenesis and tumor progression." (PMID 40612867, 2025). "Given that variations in KIFC1 gene expression in CCa cells contribute to tumor progression, and KIFC1 is highly expressed in CCa tumors, it is vita nanoluc and KIFC1 proteins to analyze the interaction with 40 genes from the USP family of deubiquitinating enzymes." (PMID 40379626, 2025). "On the contrary, KIFC1-depletion could attenuate these stimulative impacts and enhance paclitaxel sensitivity, thus suppressing tumor development." (PMID 38433242, 2024). "In addition, TUNEL staining further indicated that TRIM37 resulted in increased apoptosis to suppress tumor growth, which was inhibited by KIFC1 overexpression." (PMID 39349439, 2024). "Existing data show that high expression of KIFC1 could support the proliferation of tumor cells and improve the cell’s ability to withstand centrosome amplification and multipolar division, thereby increasing the instability of the genetic material." (PMID 37955677, 2023). "We preliminarily hypothesize that abnormal expression of KIFC1 regulates the tumor immune microenvironment to generate a poor prognosis." (PMID 38112634, 2023). "Additionally, strong correlations between KIFC1 expression and tumor immunotherapy were observed across various malignancies." (PMID 38112634, 2023). "Correlation analysis of these pathways indicates a highly significant positive correlation between KIFC1 expression and tumor proliferation pathways (Spearman coefficient = 0.72), G2/M checkpoints (Spearman coefficient = 0.79), and DNA replication pathway (Spearman coefficient = 0.63)." (PMID 37955677, 2023). "The results indicate that the expression of KIFC1 significantly increases in ESCC tissues, and the knockdown of KIFC1 could greatly reduce the proliferation capability of tumor cells, potentially having significant prognostic value." (PMID 37955677, 2023). "In addition to its function in centrosome clustering, KIFC1 has also been shown to fuel tumor progression via centrosome-independent activities." (PMID 35053604, 2022). "Interestingly, ATM and ATR phosphorylate KIFC1 upon DNA damage, in turn triggering centrosome clustering that leads to drug resistance and eventually to tumor recurrence." (PMID 35053604, 2022). "A comprehensive study of regulatory mechanisms controlling KIFC1 expression and function may therefore provide new insights into the prevention of tumor therapy resistance, recurrence, and metastasis." (PMID 33397932, 2021). "Taken together, we can infer that KIFC1 may be involved in tumor formation and development by further affecting cell proliferation through its effect on microtubules." (PMID 35111813, 2021). "Moreover, etoposide treatment promoted the KIFC1 expression in six different types of tumor cells, and etoposide, cisplatin, and IR treatments markedly enhanced KIFC1 staining in MDA-MB-231 xenograft tumors of nude mice." (PMID 33397932, 2021). "Additionally, we also found that KIFC1 gene expression was correlated with tumor stage and clinical grade." (PMID 35111813, 2021). "We also discuss evidence inferring that KIFC1 levels may be higher in premalignant lesions with a greater inclination to transform and acquire aggressive tumor intrinsic subtypes." (PMID 34945833, 2021). "We further used the CIBERSORT algorithm to investigate the tumor-infiltrating immune cells, we found that the expression of KIFC1 was negatively correlated with the infiltration of naïve B cells, M2 macrophages, resting mast cells, resting natural killer (NK) cells, and resting memory CD4+ T cells." (PMID 35111813, 2021).
tumor (continued). "KIFC1 is a kinesin motor protein involved in clustering of extra centrosomes in tumor cells." (PMID 33827418, 2021). "Inhibition of KIFC1 phosphorylation represses centrosome clustering and tumor recurrence." (PMID 33397932, 2021). "KIFC1 expression was higher in primary tumors than in matched solid (normal) tissue as well as higher in metastatic lesions than in the primary tumor indicating that metastatic PCa lesions may require higher levels of centrosome clustering mediated by KIFC1." (PMID 33760984, 2021). "In addition, we showed that pharmacological inhibition of KIFC1 phosphorylation markedly repressed centrosome clustering and tumor recurrence after chemotherapy." (PMID 33397932, 2021). "Also KIFC1 upregulation was significantly correlated with advanced pT and pTNM stage and larger tumor size in RCC tissues." (PMID 33827418, 2021). "KIFC1 is a rational tumor-selective therapeutic target and deserves further exploration." (PMID 31340839, 2019). "The tumor volume in the KIFC1 overexpression group demonstrated the opposite results." (PMID 31340839, 2019). "Using an inducible shRNA expression system with KIFC1 shRNA doxycycline-induced KIFC1 depletion resulted in significant tumor growth inhibition in both cell lines in contrast to non-targeting (NT) control cell xenografts (two-way ANOVA with Sidak’s multiple comparisons test)." (PMID 29535384, 2018). "This differential effect of high KIFC1 expression strongly suggests that elevated KIFC1 in primary sites perhaps helps tumor cells present in the primary sites to acquire karyotypic diversity (through CIN), which is more likely to lead to successful metastasis and poor survival." (PMID 26992853, 2016). "Our results indicated higher KIFC1 expression in EOC tumor samples when compared to normal tissues." (PMID 26992853, 2016). "KIFC1 expression correlated with advanced tumor grade and stage." (PMID 25028599, 2014). "Notably, both cytoplasmic and nuclear KIFC1 levels were markedly elevated in CCa tumor cells." (PMID 40379626, 2025). "However, the expression of KIFC1 increased significantly in tumor tissues with metastasis." (PMID 37789080, 2023). "Existing data show that high expression of KIFC1 could support the proliferation of tumor cells." (PMID 37789080, 2023). "However, KIFC1 also promotes tumor cell proliferation in other ways." (PMID 37789080, 2023). "Some studies suggest that KIFC1 may be involved in tumor recurrence." (PMID 35327439, 2022). "In order to evaluate whether KIFC1 expression will affect the tumor immunity, the patients were divided into high and low KIFC1 expression groups, and the immune score was calculated; results indicated that KIFC1 expression was associated with immune and stromal scores." (PMID 35111813, 2021). "Thus, we also suggest that combining KIFC1 inhibitors with existing targeted therapeutic strategies or with future specific treatments may be necessary to effectively combat oncogenesis and tumor progression." (PMID 34945833, 2021). "Furthermore, KIFC1 expression levels in EOC increased with an increase in tumor grade." (PMID 26992853, 2016). "Also, the nuclear KIFC1 WI increased with increasing tumor grade (Figure 1Bii) (p < 0.05)." (PMID 26992853, 2016). "Thus, our findings from the GSEA and Pathway analysis suggests that KIFC1 overexpression drives overexpression of genes that control mitotic checkpoints, which by generating aneuploidy, accelerate tumor progression and evolution of more aggressive phenotypes." (PMID 26992853, 2016). "After overexpression of KIFC1 and MYCBP in HeLashUSP25, the tumor growth rate was also significantly accelerated compared with that in the empty vector group." (PMID 40379626, 2025).
tumor (continued). "However, IF staining with KIFC1 and γ-tubulin antibodies further proved that the relative fluorescence intensity of KIFC1 along with γ-tubulin was significantly higher in the tumor tissues (samples 1–5) than that in the normal tissues (samples 6–10), indicating an increased number of centrosomes." (PMID 39349439, 2024). "Six of them (KIF4A, ASPM, KIF20A, KIF14, TPX2, KIF18B) are overexpressed by more than 10-fold in tumor samples and four of them (KIF11, AURKB, TPX2 and KIFC1) are essential for cell survival." (PMID 37835564, 2023). "In this study, the expression of KIFC1 was positive with immune checkpoints like CTLA4, CD276, and LAG3 in most tumor types." (PMID 38112634, 2023). "Blocking of KIFC1 phosphorylation markedly prevented the DNA damage-induced CIN and tumor recurrence." (PMID 33397932, 2021). "Therefore, KIFC1 may be a rational target for tumor therapy, which is worthy of further study." (PMID 35111813, 2021). "KIFC1 was stabilized upon phosphorylation and thus promoted centrosome clustering, CIN, and tumor recurrence both in vivo and in vitro." (PMID 33397932, 2021). "KIFC1 expression was significantly and positively correlated with TMB and tumor purity." (PMID 40612867, 2025). "Correlations between KIFC1 expression, TMB, and tumor purity were evaluated." (PMID 40612867, 2025). "Mechanistically, tumor-derived exosomal miR-205-3p downregulates AR, promoting epithelial–mesenchymal transition (EMT) and metastatic spread, while C/EBPβ-mediated activation of kinesin family member C1 (KIFC1) drives EMT and invasiveness in AR+ TNBC." (PMID 41383624, 2025). "Almost all genes were down-regulated in tumor samples, but the HN1L and KIFC1 were up-regulated." (PMID 40724805, 2025). "Inhibiting KIFC1 using the small molecule inhibitor CW069 significantly reduced tumor volume in mice bearing AR-TNBC xenografts, but not in those with triple-negative breast tumors." (PMID 40448099, 2025). "Thus, in vivo experiments confirmed that KIFC1 regulates BUB1B and the downstream Wnt/β‐catenin pathway, promoting tumour growth." (PMID 40857057, 2025). "KIFC1 levels were significantly higher in AR-low and basal-like TNBCs than in AR-high and non-basal-like TNBCs, irrespective of the stage, grade, tumor size, and lymph node status." (PMID 38003261, 2023). "Among the top 100 genes that have similar expression patterns of KIFC1 in the tumors of the TCGA cohort, the KIFC1 expression was significantly and positively correlated with KIF2C, NCAPH, KIF4A, TPX2, and CDCA5 expression in all of the tumor types in the TCGA database." (PMID 35327439, 2022). "Data from the 141 patient samples in the MSKCC dataset demonstrated KIFC1 expression was highest in tumor stage T3C but did not significantly increase with higher tumor stage (P = 0.2879)." (PMID 33760984, 2021). "Moreover, the expression of ZWINT was found to be significantly correlated with KIFC1 expression, and KIFC1 and ZWINT knockout cells were observed to reduce the tumor formation ability." (PMID 34852139, 2021). "However, a progressive increase in nuclear KIFC1 expression was observed from DH to ADH to DCIS and to IC and also correlated with increasing tumor grade." (PMID 34945833, 2021). "There was no recurrent tumor in the mice bearing KIFC1-S26A tumors and KIFC1-WT tumors combined treatment with VE-822 or CW069." (PMID 33397932, 2021). "Taken together, the effect of KIFC1 on immune cell infiltration has both positive and negative effects on tumor patients." (PMID 35111813, 2021). "KIFC1 depletion in vivo resulted in a clear reduction in tumor growth but not total inhibition of growth." (PMID 29535384, 2018). "Furthermore, we have observed that the interaction between KPNA2 and Kinesin Family Member C1 (KIFC1) facilitates the transition of BCa cells into the G2/M phase, thereby promoting tumor advancement via activation of the Phosphoinositide 3-kinase (PI3K)- Protein Kinase B (AKT) pathway." (PMID 39956902, 2025).
tumor (continued). "The tumor inhibition rate was analyzed and the tumor inhibition rates in the si-KIFC and si-KIFC+Ov-NC groups were significantly higher than those in the si-NC mice (p < 0.05), whereas ETV1 overexpression reduced the tumor inhibition rates induced by si-KIFC1 (p < 0.05)." (PMID 40612867, 2025). "To assess this hypothesis, we generated xenograft tumors using the KIFC1-WT, KIFC1-S26A, and KIFC1-S26D rescued MDA-MB-231 cell lines, and determined the tumor growth and recurrence in the presence of etoposide alone and in combination with PBS, VE-822, or CW069." (PMID 33397932, 2021). "The fact that our inducible shRNA in vivo model depletes but does not completely ablate the expression of KIFC1 may explain why inducible expression of KIFC1 shRNA impairs but does not eradicate the tumor." (PMID 29535384, 2018).
KIFC1 also shares sentences with these, for which no sentence is quoted: glioblastoma (3 papers); cervical tumor (2); head and neck squamous cell carcinoma (2); osteosarcoma (2); thyroid carcinoma (2); adenocarcinoma (1); ductal carcinoma in situ (1); dwarfism (1); esophageal squamous cell carcinoma (1); invasive ductal carcinoma (1); invasive lobular carcinoma (1); kidney chromophobe (1); leiomyosarcoma (1); melanoma (1); mesothelioma (1); metastasis (1); microcephaly (1); nasopharyngeal carcinoma (1); Obstructive azoospermia (1); ovarian epithelial tumor (1); pancreatic adenocarcinoma (1); papillary renal cell carcinoma (1); peritoneal serous adenocarcinoma (1); Pituitary adenoma (1); prostate adenocarcinoma (1); serous adenocarcinoma (1); small cell lung carcinoma (1); squamous carcinoma (1); stomach cancer (1); Thrombocytopenia (1).
A further 1 disease shares a sentence with KIFC1 in 1 paper.